AADAT (aminoadipate aminotransferase)
Description:
Transaminase with broad substrate specificity. Has transaminase activity towards aminoadipate, kynurenine, methionine and glutamate. Shows activity also towards tryptophan, aspartate and hydroxykynurenine. Accepts a variety of oxo-acids as amino-group acceptors, with a preference for 2-oxoglutarate, 2-oxocaproic acid, phenylpyruvate and alpha-oxo-gamma-methiol butyric acid. Can also use glyoxylate as amino-group acceptor (in vitro).
Synonyms: KAT2; KYAT2; KATII
Tractability: Small molecule: a structure with a bound ligand is known; a high-quality ligand is known; it has a high-quality binding pocket; it belongs to a druggable protein family. Antibody: the Human Protein Atlas places it where antibodies can reach. PROTAC: ubiquitination databases record sites on it; its protein half-life has been measured; a small molecule that binds it is known.
Target class: Enzyme; Transferase
Gene: Protein-coding gene on chromosome 4 (170,060,219 to 170,091,699, reverse strand). Ensembl gene ENSG00000109576.
Subcellular location: Mitochondrion
Subcellular location (Human Protein Atlas): Plasma membrane; Vesicles
Pathways (Reactome):
Metabolism: Lysine catabolism; Tryptophan catabolism
Gene Ontology:
Molecular function: 2-aminoadipate transaminase activity; glycine:2-oxoglutarate aminotransferase activity; kynurenine-glyoxylate transaminase activity; kynurenine-oxoglutarate transaminase activity; methionine-glyoxylate transaminase activity; aromatic-amino-acid-glyoxylate transaminase activity; pyridoxal phosphate binding; transaminase activity
Biological process: amino acid catabolic process; L-lysine catabolic process
Cellular component: mitochondrion; cytosol; mitochondrial matrix
Genetic constraint (gnomAD): Loss-of-function variants: 13 observed, 33.05 expected, observed/expected ratio (o/e) 0.39, 90% interval 0.25 to 0.62. The upper end of that interval is the gene's LOEUF score, 0.62, which puts it in group 2 of 6, group 1 being the genes least tolerant of losing a copy. Missense variants: 291 observed, 402.21 expected, observed/expected ratio (o/e) 0.72, 90% interval 0.66 to 0.8. Synonymous variants: 131 observed, 136.71 expected, observed/expected ratio (o/e) 0.96, 90% interval 0.83 to 1.11.
Homologues: Orthologues: chimpanzee AADAT (99% identical), macaque AADAT (97% identical), dog AADAT (83% identical), rabbit AADAT (82% identical), guinea pig AADAT (75% identical), pig AADAT (74% identical), mouse Aadat (74% identical), rat Aadat (69% identical), tropical clawed frog aadat (63% identical), zebrafish aadat (59% identical). Paralogues in human: ACCSL (20% identical), ACCS (19% identical), TAT (18% identical), GPT2 (16% identical), GPT (16% identical), KYAT3 (15% identical), KYAT1 (14% identical).
Diseases named in the same sentence as AADAT in open-access papers:
AADAT is named in the same sentence as 40 diseases in open-access papers, as found by Europe PMC text mining. Sharing a sentence is not in itself a finding about the gene and the disease. The quoted sentences say what the papers report.
colitis (2 papers, 2022 to 2025). Inflammation of the colon. "Additionally, the use of recombinant aminoadipate aminotransferase (AADAT), an enzyme involved in XANA and KYNA production, modulated tryptophan metabolism and conferred protective effects in DSS-induced colitis models." (PMID 40243712, 2025).
meningitis (2 papers, 2011 to 2024). A disorder characterized by acute inflammation of the meninges of the brain and/or spinal cord. "AADAT has been firstly investigated in immune response in meningitis patients." (PMID 39043735, 2024).
neuroblastoma (2 papers, 2011 to 2022). Neuroblastoma (NB) is the most common solid, extracranial childhood tumor. "Additionally, the AADAT and GOT2, the KAT’s enzymes that lead to a KYNA formation, presented a decreased expression among the different tumors compared to the brain cortex, except in the neuroblastoma group, in which the expression of AADAT is higher compared to the brain cortex." (PMID 36355137, 2022).
bacterial meningitis (1 paper, 2019). Inflammation of the membranes surrounding the brain and spinal cord due to a bacterial infection. "Variations of the AADAT gene encoding the KATII enzyme were found to be associated with bacterial meningitis, changes in KYNU are believed to be related to essential hypertension and xanthurenic aciduria." (PMID 31781097, 2019). "Investigation of genetic variants of another KP gene, AADAT, that encodes KATII, revealed that in a SNP (rs1480544), a C to T change in the intronic region of the gene might be associated with bacterial meningitis (BM)." (PMID 31781097, 2019).
hypothyroidism (1 paper, 2018). Abnormally low levels of thyroid hormone. "Here, the authors carry out genome-wide meta-analysis for thyroid hormone (TH) levels, hyper- and hypothyroidism and identify SLC17A4 as a TH transporter and AADAT as a TH metabolizing enzyme." (PMID 30367059, 2018).
ischemic stroke (1 paper, 2021). A stroke disorder caused by obstruction of blood flow to the brain, due to thrombotic (local blood clot formation) or embolic (due to a blood clot or other material traveling from another site) event. "We present data demonstrating associations between ischemic stroke and variants of four genes (TPH1, IDO1, KYAT1 and AADAT) encoding enzymes of Trp metabolism." (PMID 34680558, 2021). "Furthermore, we also wished to learn whether changes are detectable in the expression of TPH1, TPH2, IDO1, KYAT1 and AADAT genes in peripheral blood samples (PBS) of ischemic stroke patients during the course of the disease." (PMID 34680558, 2021).
learning disabilities (1 paper, 2021). "In the current study, we measured the expression levels of three genes involved in tryptophan metabolic pathways, which are MAOA (serotonin pathway) along with two genes within the kynurenine pathway (HAAO and AADAT) in both children with ASD and learning disabilities." (PMID 33767242, 2021). "Our objective was to evaluate some aspects of tryptophan metabolism in ASD children (N = 45) compared to children with learning disabilities (N = 44) and healthy controls (N = 40) by measuring the expression levels of the MAOA, HAAO and AADAT genes using real-time RT-qPCR." (PMID 33767242, 2021). "Relative to healthy control children, our data detected a significant decrease in the expression levels of MAAO, HAAO and AADAT genes among children with ASD, but indifferent expression levels in children with learning disabilities relative to both controls and ASD children." (PMID 33767242, 2021).
tumor (6 papers, 2020 to 2026). "Our analysis also revealed AADAT enzyme over-expression in the majority of CRC tumours." (PMID 40348885, 2025). "Besides this, it was shown that the AADAT and GOT2 enzymes that represent the ‘short branch’ of the KP leading to the KYNA formation presented expression levels below non-tumor tissue." (PMID 36355137, 2022). "In vivo, malate supplementation in drinking water phenocopied AADAT knockdown, restored the response to paclitaxel plus anti-PD-1 therapy in multiple independent syngeneic TNBC models with de novo or acquired resistance to immunotherapy, reduced tumor burden, and prolonged survival." (PMID 41659489, 2026).
cancer (3 papers, 2019 to 2025). A tumor composed of atypical neoplastic, often pleomorphic cells that invade other tissues. "To validate the prediction that activating these enzymes may help reduce cancer cell growth, we over-expressed two related genes, AASS and AADAT, in a series of cancer cell lines with different tissues-of-origin and genetic backgrounds." (PMID 31601242, 2019).
AADAT also shares sentences with these, for which no sentence is quoted: schizophrenia (12 papers); glioma (5); cognitive deficits (4); infection (4); cognitive diseases (2); depression (2); neurological diseases (2); Stroke (2); acute respiratory distress syndrome (1); Alzheimer disease (1); Anxiety (1); autism (1); brain disorder (1); essential hypertension (1); glioblastoma (1); Hepatic cysts (1); hepatocellular carcinoma (1); Huntington disease (1); inflammatory bowel disease (1); ischemia (1); kidney failure (1); leukemia (1); migraine (1); neurodevelopmental disorder (1); pancreatic cancer (1); psychiatric disorder (1); rheumatoid arthritis (1); Sepsis (1); sitosterolemia (1); virus infection (1).
A further 1 disease shares a sentence with AADAT in 1 paper.